CNR1 (cannabinoid receptor 1)
Diseases named in the same sentence as CNR1 in open-access papers (continued):
Sharing a sentence is not in itself a finding about the gene and the disease.
Obesity (continued). "Interestingly, other variants also known to influence reward/addiction associated processes or eating related behaviour such as OPRD1, BDNF, GHRL and CNR1, also revealed evidence of being associated with overweight/obesity or development to an adverse metabolic status." (PMID 26445370, 2015). "We assessed only six common polymorphisms of CNR1 but there are also several other polymorphisms that can be associated with adverse metabolic and cardiovascular profiles, such as rs2023239, rs806378, rs806365, and rs10485179, whose relationship with obesity, type 2 DM, and IR was revealed." (PMID 25136364, 2014). "For example, a variety of options have showed efficiency for treating BED, including antidepressants, anticonvulsants, opioid receptor antagonists, and anti-obesity medicines, such as cannabinoid receptor 1 (CB1) antagonists and GLP-1 analogs." (PMID 39891848, 2025). "Rimonabant is a selective blocker of the cannabinoid receptor 1 (CB1) and is used as a treatment for obesity management which reduces appetite." (PMID 38715796, 2024). "The G‐protein‐coupled human cannabinoid receptor 1 (CB1) is a promising therapeutic target for pain management, inflammation, obesity, and substance abuse disorders." (PMID 38298116, 2024). "In zebrafish, male exposure to both 500 μg/L BPA and tetrabromobisphenol (TBBPA) significantly altered the hepatic metabolism, induced liver steatosis and obesity, and increased appetite signals by activating the transcription of cnr1." (PMID 39595979, 2024). "The cannabinoid receptor 1 (CB1) antagonist, rimonabant has demonstrated efficacy in treating obesity albeit with the risk of significant neuropsychiatric side effects." (PMID 37415200, 2023). "Antagonism of cannabinoid receptor 1 (CB1), which is upregulated in obesity, promotes weight loss and decreases obesity-associated co-morbidities." (PMID 36232744, 2022). "Medications used for obesity treatment such as cannabinoid receptor 1 (CB1) antagonist Rimonabant with side effects of either depression or gastrointestinal reactions, respectively, resulting in low patient compliance." (PMID 36111301, 2022). "Endocannabinoid signaling is overactive in obesity, with some effects abated by antagonism of cannabinoid receptor 1 (CB1)." (PMID 36232744, 2022). "A temporal transcriptional regulation of CNR1 gene was also proved in the HYP of rats exposed to diet-induced obesity." (PMID 33401515, 2021). "A cross-sectional study of 667 subjects identified racial differences in CNR1 and FAAH polymorphisms associated with obesity." (PMID 34220722, 2021). "Again, conditional mutant mice, with CNR1 deletion in forebrain and sympathetic neurons, known to control energy balance, are resistant to diet-induced obesity and display a lean phenotype." (PMID 33401515, 2021). "In fact, CB1R is present in human subcutaneous adipocytes, encoded by the CNR1 gene, alterations in which, related to obesity traits, are frequently described in the literature." (PMID 33530406, 2021). "The important role of the ECS in the pathophysiology of obesity can be proven by the fact that a blockade of CNR1 by means of rimonabant leads to a significant reduction in food intake and weight loss." (PMID 33530406, 2021). "By investigating the importance of the eCB system in the browning process during obesity, studies in mice showed that genetic depletion of Cnr1 enhances energy expenditure by the BAT." (PMID 34064024, 2021). "The analysis of ECS components gene expression revealed a significant and selective increase in CNR1 mRNA levels at the beginning of obesity development (5 weeks on HFD) as well as after 21 weeks of exposure, when the phenotype was already well-established." (PMID 33401515, 2021). "Cannabinoid receptor‐1 (CB1) represents a potential drug target against conditions that include obesity and substance abuse." (PMID 31608546, 2020).
Obesity (continued). "Despite the great amount of research showing CB1 levels dysregulation centrally in animal models of obesity, there is less information about altered hypothalamic Cnr1 mRNA levels, which anyhow have been reported by some." (PMID 31258545, 2019). "At the clinical level, it seems noteworthy that an increased CNR1 expression in obesity has been shown at the peripheral level, but never in blood samples from human subjects." (PMID 31258545, 2019). "A significant and selective increase in type 1 cannabinoid receptor gene (Cnr1) expression was observed at the beginning of obesity development (5 weeks on high fat diet) as well as after 21 weeks of high diet exposure." (PMID 31258545, 2019). "At any rate, this is the first report showing DNA methylation of Cnr1 in obesity, whereas others have already addressed MOP epigenetic regulation in mice reward-related brain regions of the offspring of pregnant dams exposed to chronic high-fat diet." (PMID 31258545, 2019). "Since, the discovery of the cannabinoid receptor 1 (CB1R) system, and the subsequent disclosure of its critical roles in the developing and progression of obesity, the pursuit for effective CB1R antagonists to manage morbid obesity haven’t lost its momentum." (PMID 29615900, 2018). "CNR1 regulates food intake in the hypothalamus and in obesity the endocannabinoid/CNR1 system is upregulated, both centrally and peripherally." (PMID 27858284, 2017). "CNR1 is highly expressed in the central nervous system and has been a drug target for the treatment of obesity." (PMID 27858284, 2017). "Although the association between the central and peripheral levels of CNR1 and obesity has been demonstrated, it is uncertain if an increase of CNR1 in adipose tissue is sufficient to induce changes in glucose and lipid metabolism." (PMID 27858284, 2017). "In 2006, a potent and selective CNR1-antagonist, rimonabant, was approved for treatment of obesity and for overweight patients with metabolic comorbidities such as T2D." (PMID 27858284, 2017). "In our study with freshly harvested samples we had well-controlled T2D subjects with a tight BMI and gender matching with control subjects, which allowed us to strictly compare the disease vs. the influence of obesity on CNR1 gene expression." (PMID 27858284, 2017). "Cannabinoid receptor 1 (CB1R) antagonists appear to be promising drugs for the treatment of obesity, however, serious side effects have hampered their clinical application." (PMID 26416158, 2015). "The hepatic expression level of cannabinoid receptor 1 (CB1), the target of anti-obesity drug rimonabant can also be induced by the treatment of RA via activation of RAR-γ, indicating the connection between the nutritional signals and endocannabinoid pathways." (PMID 23028851, 2012). "In vitro studies indicate a regulatory role for the cannabinoid receptor 1 (CB1) in adipocyte function and CB1-receptor deficient (CB1-/-) mice are resistant to high fat diet-induced obesity." (PMID 22201701, 2011). "Since the cannabinoid receptor CB1 plays a key role in the pathogenesis of obesity by increasing food intake and reducing energy expenditure, we first characterized Cnr1 expression in brain, adipose tissue and liver." (PMID 19513120, 2009). "Additionally, the CNR1 (cannabinoid receptor 1) has been identified as a promising drug target for the treatment of obesity, with CNR1 knockout in mice resulting in improvements in insulin resistance, ER stress, and lipid accumulation." (PMID 38246999, 2024). "A review of these data found no SNPs in FAAH, MGLL, or DAGLA/DAGLB that showed genome-wide significant association (p < 5 × 10−8) with obesity or related outcomes (no SNPs in CNR1 either)." (PMID 34959715, 2021). "The ECS is important in the control and regulation of body weight, since stimulation of CB1 (cannabinoid receptor 1) by anandamide (AEA) and 2-arachidonoylglyceride (2-AG) is associated with increased appetite, higher food intakes, weight gain, and obesity." (PMID 32680548, 2020).
Obesity (continued). "Additionally, methylation at CNR1 promoter of subjects that were obese for more than 5 years was higher than that of humans with obesity for a shorter time." (PMID 31258545, 2019). "Over-activation of endocannabinoids and increased expression of cannabinoid receptor 1 (CB1R) in adipose tissue had been confirmed under condition of morbid obesity, and CB1R had been proved to be an attractive target in developing novel anti-obesity drugs." (PMID 29731737, 2018). "Given the role of CNR1 in obesity, antagonists have been developed as anti-obesity drugs." (PMID 27858284, 2017). "In addition, others have found reduced CNR1 expression in adipose tissue with obesity, but only post-menopausal women or surgical patients with variation in age and concomitant medication were included." (PMID 27858284, 2017). "The value of Dagla as an anti-obesity target would be enhanced if the favorable metabolic phenotype shared by Dagla and Cnr1 KO mice was not linked to the undesirable neuropsychiatric effects associated with rimonabant." (PMID 26082754, 2015). "We hypothesized that polymorphic variants of the CB1 gene (CNR1) might be associated with differences in EC activity and function and potentially contribute to individual susceptibility to obesity and related complications." (PMID 25136364, 2014). "CNR1 is associated with low HDL dyslipidemia and a common haplotype of CNR1 could be a protective factor of obesity-related dyslipidemia." (PMID 24621099, 2014). "Cannabinoid receptor 1 antagonist rimonabant has been used to effectively treat obesity." (PMID 22701720, 2012). "One of the most well-characterized longitudinal cohort studies in the U.S, the Framingham Heart Study, recently failed to observe any association between CNR1 and obesity." (PMID 21209828, 2010). "Even though the CNR1 SNP rs1049353 has not been analysed in patients with AN before, the G-allele of rs1049353 was recently found to be associated with obesity in a small case-control study comprising obese and normal weight Italians." (PMID 19014633, 2008). "Conditional expression of cannabinoid receptor 1 (Cb1r) in the liver of the transgenic line Tg(-2.8fabp10a: Tetoff-Cb1r-2 A-EGFP)two23 promotes hepatic lipid accumulation and steatosis, which is important for food intake, weight gain, and various pathological features linked to obesity." (PMID 41134486, 2025). "However, the literature has been inconsistent with respect to CNR1 polymorphisms and obesity-related markers, with many studies not finding any relevant association with CNR1 gene variants." (PMID 33401515, 2021). "Additionally leptin resistance, a condition causing food intake alteration and consequent obesity development, has been linked to the over-activation of the ECS, with a sex-specific epigenetic modulation of cnr1, the gene encoding CB1, following maternal high fat diet (HFD)." (PMID 32927614, 2020). "Therefore, insulin resistance, rather than obesity, seems to be associated with CNR1 gene expression in both SAT and OAT." (PMID 27858284, 2017). "Thus, the concomitant increase in expression of gastric CNR1 and LEP in patients with hepatic inflammation seen in this study may be another indication of contribution of peripheral leptin resistance to obesity-associated NASH." (PMID 24716593, 2014). "Accordingly, PLA2G2A and PLA2G4A genes were up-regulated by omega-3 polyunsaturated fatty acids supplementation, whereas SLC27A2, CNR1, DAGLA, MGLL, FAAH, SLC27A1, and SLC27A2 genes were found to be down-regulated in people living with healthy obesity." (PMID 38024342, 2023). "scWAT gene expression of SLC27A2, CNR1, DAGLA, MGLL, FAAH, SLC27A1 and SLC27A2 were lower in individuals living with healthy obesity." (PMID 38024342, 2023). "A cannabinoid receptor 1(CB1) influences appetitive behaviour and energy metabolism, and therefore it was proposed to be a target for anti-obesity treatment." (PMID 36297390, 2022).
Obesity (continued). "Cannabinoid receptor 1 (CB1) is a therapeutically relevant drug target for controlling pain, obesity, and other central nervous system disorders." (PMID 35227761, 2022). "DNA methylation changes at human CNR1 and OPRM1 gene promoters in controls (CTRL) and humans with obesity." (PMID 31258545, 2019). "We sought to extend the analysis of DNA methylation at CNR1 and OPRM1 promoters in the preclinical animal model to a group of humans with obesity and matched healthy controls (CTRLs)." (PMID 31258545, 2019). "We also observed the DNA methylation levels on CNR1 and OPRM1 gene promoters in humans with obesity and Ctrl stratified for gender." (PMID 31258545, 2019). "In obesity, the endogenous endocannabinoid anandamide (AEA) promotes appetite and reduces energy expenditure through the activation of cannabinoid receptor 1 (CB1)." (PMID 30707678, 2019). "In order to assess the impact of CNR1 variability on the development of dyslipidemia in the community, we genotyped this locus in all subjects with class III obesity (body mass index >40 kg/m2) participating in a population-based biobank of similar ancestry." (PMID 21209828, 2010). "In a recently reported phase 1b study, the novel peripherally acting Cannabinoid Receptor-1 (CB1R) inverse agonist, INV-202 (monlunabant), was evaluated in a placebo-controlled trial over 28 days in participants with obesity and features of metabolic syndrome and glucose intolerance." (PMID 39997710, 2025). "Specific deletion of cannabinoid receptor 1 in renal proximal tubule cells, although not protecting mice from obesity, significantly attenuates obesity-induced renal lipid accumulation and renal dysfunction, injury, inflammation, and fibrosis." (PMID 39113692, 2024). "Rimonabant was authorized in Europe in 2006 as an anti-obesity medication and then withdrawn by the European Medicines Agency (EMA) in 2009 leading to the termination of the development of other cannabinoid receptor 1 (CB1) blockers for obesity." (PMID 38265519, 2024). "Obesity is also characterized by a relevant increase of endocannabinoids levels in both plasma and adipose tissue, decreased expression of FAAH, and altered expression of cannabinoid receptor 1 (CB1)." (PMID 37091842, 2023). "Thus, here we clearly show the relevant role of CNR1 and OPRM1 transcriptional regulation as a possible biomarker for obesity and, due to the reversible nature of the epigenetic hallmark, our data open new avenue for environmental strategies of intervention." (PMID 31258545, 2019). "These alterations in genes regulation could contribute to the development of the obese phenotype, and we thus suggest CNR1 and OPRM1 epigenetic modulation as possible biomarkers of obesity development." (PMID 31258545, 2019). "In contrast, increased CNR1 expression with obesity has been shown in some reports, but no multivariate corrections were performed and the number of subjects per group is limited (<10)." (PMID 27858284, 2017). "Importantly, a common CNR1 haplotype, H3, was further protective against the marked reduction in HDL-C that occurs in severe obesity (BMI≥40 kg/m2)." (PMID 22567136, 2012). "It is important to note, however, that this relationship is not driven by a direct effect of CNR1 on obesity." (PMID 21209828, 2010). "Many investigations have demonstrated the positive effects of antagonizing cannabinoid receptor 1 (CB1R) in metabolic diseases such as fatty liver disease, obesity, and diabetes mellitus, but the role of cannabinoid receptor 2 (CB2R) in such diseases is relatively unknown." (PMID 35115945, 2021). "With the aim to extend the study of CB1 and MOP receptors to human obesity, we assessed whether PBMCs might mirror central nervous system defects, and we then evaluated DNA methylation at CNR1 and OPRM1 gene promoters in PBMCs of humans with obesity." (PMID 31258545, 2019).
Obesity (continued). "Increased hepatic expression of Gpr119 and Cd68, but not Cnr1 was also detected in mice with CL-HFS-induced NASH and human patients with obesity and NASH." (PMID 36646715, 2023).
Anxiety (198 papers, 2007 to 2026). Intense feelings of nervousness, tension, or panic often arise in response to interpersonal stresses. "According to the general view, the invalidation of the Cnr1 gene that encodes the CB1 receptor increases anxiety." (PMID 37958761, 2023). "The same FAAH polymorphism (rs324420), combined with the minor allele combination of rs7209436C, rs110402, and rs242924G of the CNR1 gene, was associated with an increased risk of developing anxiety." (PMID 35563156, 2022). "On the other hand, CNR1 rs7766029 polymorphism was correlated with psychosocial adverse event exposure, increasing the likelihood of developing anxiety or depression." (PMID 35563156, 2022). "It elicits its psychoactive effects by activating the cannabinoid receptor 1 (CB1), a main component of inhibitory synaptic feedback processes and synaptic plasticity, underlying learning and memory, reward, stress, and anxiety." (PMID 34526890, 2021). "Cannabinoid use induces symptoms, such as anxiety, memory loss and chronic pain, which is associated with cannabinoid receptors 1 (CNR1) and 2 (CNR2)." (PMID 35140610, 2021). "Mice genetically deficient for the CB1 receptor (Cnr1−/−) show phenotypes similar to clinical symptoms of anxiety and depressive disorders and show certain differences in social behavior." (PMID 32997200, 2021). "Cnr1-/- dams show deficits in maternal care (pup retrieval), which is likely caused by their increased anxiety state and correlated with reduced oxytocin receptor and BDNF expression in the hippocampus." (PMID 32997200, 2021). "These previous studies established that genetic disruption of cannabinoid receptor 1 caused anxiety-like behavior in numerous paradigms including elevated plus maze and light-dark tests." (PMID 29304078, 2018). "Three of the eight subjects with rare CNR1 variants and headaches in our study also have memory disorders (mainly short term memory), and two of those have comorbid anxiety and sleep disorders." (PMID 29145497, 2017). "The CNR1 variants were found to be associated with headache (including migraine), sleep and memory disorders, alone or in combination with anxiety, compared to a control set of 950 randomly selected patients without such CNR1 variants." (PMID 29145497, 2017). "Specifically, they found that individuals who possessed the short variant of the serotonin transporter, coupled to the GG homozygous allele of the rs2180619 polymorphism of the CNR1 gene, exhibited dramatically higher levels of anxiety." (PMID 24286185, 2013). "SUZ12, TCF7L1, and BCL3 could bind to the CNR1 promoter region to regulate the expression of CNR1, which was associated with anxiety and chronic pain." (PMID 32434423, 2020). "In our present study we demonstrated that variants in GABRA6 and CNR1 genes, previously implicated in both stress and depression, interact with particular types of recent life stressors in influencing depression and anxiety." (PMID 31024264, 2019). "Thus, the aim of the present study was to investigate the effect of the interaction between different types of recent life events and GABRA6 or CNR1 gene variants on recent depressive/anxiety symptoms in a large European general population sample." (PMID 31024264, 2019). "Interestingly, 2/5 subjects with a CNR1 p.Ala419Glu variant (ExAC MAF = 0.00038) had the shared phenotypes: anxiety, sleep disorder, and abnormality of the autonomic nervous system." (PMID 29145497, 2017). "Given that our RNAscope analysis revealed dense Cnr1 mRNA expression (encoding CB1R) in both PrL-projecting and ovBNST-projecting AI glutamatergic neurons, it is possible that eCB signaling within the vAI-PrL and dAI-ovBNST circuits regulates the comorbidity of headache and anxiety." (PMID 41377021, 2025).